ADA2 (adenosine deaminase 2)
Description:
Adenosine deaminase that may contribute to the degradation of extracellular adenosine, a signaling molecule that controls a variety of cellular responses. Requires elevated adenosine levels for optimal enzyme activity. Binds to cell surfaces via proteoglycans and may play a role in the regulation of cell proliferation and differentiation, independently of its enzyme activity.
Synonyms: ADGF; CECR1; IDGFL; PAN; SNEDS; VAIHS
Tractability: Small molecule: a structure with a bound ligand is known; it has a high-quality binding pocket. Antibody: UniProt places it where antibodies can reach, with high confidence; its Gene Ontology location is reachable by antibodies, with high confidence; UniProt predicts a signal peptide or a membrane-spanning region. PROTAC: ubiquitination databases record sites on it.
Gene: Protein-coding gene on chromosome 22 (17,178,790 to 17,258,235, reverse strand). Ensembl gene ENSG00000093072.
Subcellular location: Secreted
Pathways (Reactome):
Immune System: Neutrophil degranulation
Metabolism of proteins: Surfactant metabolism
Gene Ontology:
Molecular function: adenosine deaminase activity; adenosine receptor binding; protein homodimerization activity; proteoglycan binding; zinc ion binding; growth factor activity; deaminase activity
Biological process: adenosine catabolic process; inosine biosynthetic process; signal transduction
Cellular component: extracellular region; azurophil granule lumen
Genetic constraint (gnomAD): Loss-of-function variants: 26 observed, 41.02 expected, observed/expected ratio (o/e) 0.63, 90% interval 0.46 to 0.88. The upper end of that interval is the gene's LOEUF score, 0.88, which puts it in group 3 of 6, group 1 being the genes least tolerant of losing a copy. Missense variants: 600 observed, 622.18 expected, observed/expected ratio (o/e) 0.96, 90% interval 0.9 to 1.03. Synonymous variants: 195 observed, 228.62 expected, observed/expected ratio (o/e) 0.85, 90% interval 0.76 to 0.96.
Homologues: Orthologues: chimpanzee ADA2 (99% identical), macaque ADA2 (94% identical), pig ADA2 (69% identical), tropical clawed frog ada2 (49% identical), zebrafish ada2a (49% identical), zebrafish ada2b (45% identical), Drosophila melanogaster Adgf-A (38% identical), Drosophila melanogaster Adgf-D (37% identical), Drosophila melanogaster Adgf-E (37% identical), Drosophila melanogaster Adgf-C (36% identical), Drosophila melanogaster Adgf-B (36% identical), Drosophila melanogaster Adgf-A2 (31% identical). Paralogues in human: ADA (15% identical), MAPDA (13% identical).
Diseases named in the same sentence as ADA2 in open-access papers:
ADA2 is named in the same sentence as 193 diseases in open-access papers, as found by Europe PMC text mining. Sharing a sentence is not in itself a finding about the gene and the disease. The quoted sentences say what the papers report.
Immunodeficiency (40 papers, 2016 to 2026). Failure of the immune system to protect the body adequately from infection, due to the absence or insufficiency of some component process or substance. "ADA2 deficiency was more recently classified in 2014, with the complex phenotype including early onset stroke, vasculitis, and immunodeficiency." (PMID 41601962, 2026). "These complications highlight the critical need for early intervention to manage stroke risks, vasculopathy, and immune deficiencies in ADA2 deficiency." (PMID 39239002, 2024). "We present the case of a 24-year-old male with CNS granulomatosis due to an immunodeficiency syndrome which was identified as deficiency of adenosine deaminase 2 (DADA2) as a cause of brainstem infarction." (PMID 37306896, 2023). "We present the case of a 24-year-old male with CNS granulomatosis due to an immunodeficiency syndrome which was identified as deficiency of adenosine deaminase 2 (DADA2) as a cause of cerebellar syndrome and brainstem infarction." (PMID 37306896, 2023). "Targeted next-generation sequencing (NGS) for autoinflammatory diseases and immunodeficiencies revealed the homozygous Leu183Pro ADA2 mutation, which was confirmed by Sanger analysis." (PMID 36159847, 2022). "Although rare, ADA2 deficiency should be considered in patients with early-onset stroke, especially with concomitant manifestations of inflammatory features or immunodeficiency." (PMID 36528591, 2022). "Given the complex clinical picture and the family history, a large NGS diagnostic panel for autoinflammatory diseases and immunodeficiencies was performed revealing the homozygous c.1358A>G mutation in ADA2 (CECR1) gene described in literature as pathogenetic." (PMID 36096831, 2022). "Although these are associations, they invite a large prospective survey on the immunophenotype of ADA2-deficient patients to further our understanding of the variable immunodeficiency manifestations." (PMID 34657246, 2021). "ADA1 deficiency leads to a severe combined immunodeficiency, and ADA2 deficiency can create several abnormalities, including vasculitis Behçet’s-like disease, immunodeficiency due to hypogammaglobulinemia, or cytopenias." (PMID 33046093, 2020). "Whereas cytopenia and hypogammaglobulinemia associated with varying degrees of immunodeficiency have commonly been described in ADA2-deficient patients, signs of autoimmunity have only rarely been recognized." (PMID 28830446, 2017). "However, some cases have been associated with underlying immune system disorders, such as adenosine deaminase 2 (ADA2) deficiency or Griscelli syndrome." (PMID 39066167, 2024). "The clinical phenotype of human ADA2 deficiency includes not only recurrent fevers and vasculitis (ranging from livedo racemosa to polyarteritis nodosa and lacunar stroke) but also immunodeficiency and cytopenia, either due to autoimmunity or bone marrow (BM) failure and hematological malignancy." (PMID 34657246, 2021). "Deficiency of adenosine deaminase 2 (DADA2) causes a complex phenotype of autoinflammation and immunodeficiency." (PMID 41866403, 2026). "Background and Clinical Significance: Deficiency of Adenosine Deaminase 2 (DADA2) is a rare monogenic vasculopathy characterised by systemic inflammatory and immunodeficiency features." (PMID 41594165, 2026). "Deficiency of ADA2 (DADA2), in contrast, causes a complex phenotype of autoinflammation and immunodeficiency." (PMID 39956283, 2025). "ADA1 and ADA2 are two adenosine deaminases in humans, and changes in ADA activity are associated with pathological conditions, such as immune disorders and cancer." (PMID 40936927, 2025). "Mutations in the human ADA2 gene cause autoinflammatory diseases, such as deficiency of adenosine deaminase 2 (DADA2), which is characterized by recurrent fever, livedoid rash, stoke, immunodeficiency, and bone marrow failure." (PMID 35990631, 2022).
Immunodeficiency (continued). "Deficiency of adenosine deaminase 2 (DADA2) is an autosomal recessive disease associated with a highly variable clinical presentation, including vasculitis, immunodeficiency, and hematologic manifestations, potentially progressing over time." (PMID 36248833, 2022). "Various clinical manifestations of ADA2 deficiency (VAIHS, OMIM#615688) include vasculopathy, skin manifestations, neuropathy, immunodeficiency, and hematology." (PMID 35261770, 2022). "Deficiency of adenosine deaminase 2 (DADA2) is an autosomal recessive disease associated with a highly variable clinical presentation, including systemic vasculitis, immunodeficiency, and cytopenia." (PMID 36159847, 2022). "Studies have found a dramatic increase in ADA2 activity in immune diseases such as systemic lupus erythematosus and tuberculosis, while ADA2 levels in pleural effusions have also been used as a marker for tuberculosis." (PMID 36225941, 2022). "The diverse clinical phenotype and weak genotype–phenotype correlations further complicate the identification of shared cellular mechanisms that cause inflammation, immunodeficiency, and bone marrow failure in the absence of functional ADA2." (PMID 39956283, 2025). "Deficiency of adenosine deaminase 2 (DADA2) is a rare monogenic autoinflammatory disease, whose clinical phenotype was expanded since the first cases, originally described as mimicker of polyarteritis nodosa, with immunodeficiency and early-onset stroke." (PMID 37179309, 2023). "Furthermore, in a proband suspected to have autosomal recessive vasculitis, autoinflammation, immunodeficiency, and hematologic defects syndrome (VAIHS; OMIM: #615688), exome sequencing (ES) only identified one missense variant in the causative gene ADA2." (PMID 36672937, 2023). "Deficiency of adenosine deaminase type 2 (DADA2) is an autosomal recessive monogenic AID caused by ADA2 (formerly known as CECR1) mutations and was first described in 2014 in patients with mild immune deficiency, systemic inflammation, and central nervous system vasculopathy." (PMID 33042144, 2020). "The deficiency of Adenosine Deaminase 2 (DADA2) is a new autoinflammatory disease characterised by an early onset vasculopathy with livedoid skin rash associated with systemic manifestations, CNS involvement and mild immunodeficiency." (PMID 27609179, 2016). "Therefore, for children with PAN-like phenotypes, DADA2 should be considered, and screening should include ADA2 level measurement and basal immune deficiency testing to rule out potential organ damage." (PMID 40181996, 2025). "Additionally, expanding ADA2 RAT applications to identify immune disorders and cancers may require comparative studies alongside traditional ELISA-based assays to establish the broader clinical utility of these methods." (PMID 40936927, 2025). "Associated with biallelic mutations in ADA2 (previously CECR1, cat eye syndrome chromosome region, candidate 1), it was first described in 2014, as a disease similar to polyarteritis nodosa with early‐onset stroke, systemic inflammation, vasculopathy, and mild immunodeficiency." (PMID 37647436, 2023). "The use of tumour necrosis factor (TNF) inhibitors in the treatment of ADA2 deficiency has significantly improved patient care; however, the response to therapy is not always favourable, especially in cases with immunodeficiency and haematological manifestations." (PMID 36528591, 2022). "All these findings indirectly support that the Ada2 deficiency-related bony alterations may also occur as a non-immunological manifestation, not entirely explainable as related to the observed immunodeficiency." (PMID 34361096, 2021). "Bi-allelic loss-of-function mutation in ADA2 located on chromosome 22q11.1 results in loss of enzyme activity of adenosine deaminase 2 (ADA2), a dimeric 57 kDa extracellular isoform of adenosine deaminase 1 (ADA1: deficiency of which causes severe combined immunodeficiency)." (PMID 31291964, 2019).
Immunodeficiency (continued). "One such biomarker is adenosine deaminase 2 (ADA2), an enzyme that converts adenosine into inosine and is elevated in cancer and immune diseases." (PMID 40936927, 2025). "Patients with very low or absent ADA2 enzymatic activity also present with severe marrow failure and/or immunodeficiency." (PMID 35529868, 2022). "His parents were heterozygous for the same mutation; a 3 year old female sibling was bi-allelic wild type for ADA2; and there was no family history of vasculitis, autoimmunity or immunodeficiency." (PMID 31291964, 2019). "Although the protein assay for the ADA2 activity has been used to assess disease activity in many inflammatory conditions, ADA2 was never considered a candidate gene for any immune disorder." (PMID 29951947, 2018). "DADA2 is an immune system disease recognized as a mimic of polyarteritis polyarteritis nodosa (PAN) with systemic autoinflammatory vasculopathy, often presenting at infancy/early childhood, in fact caused by the absence of ADA2 enzymatic activity." (PMID 34361096, 2021).
vasculitis (34 papers, 2014 to 2026). "DADA2 (deficiency of adenosine deaminase 2) is a vasculitis disease caused by autosomal-recessive loss-of-function mutations in the ADA2 gene." (PMID 40429912, 2025). "Deficiency of adenosine deaminase 2 (DADA2) patients has high similarity to pan vasculitis manifestation." (PMID 39239002, 2024). "DADA2 is increasingly being recognized as a monogenic etiology for PAN with systemic inflammation and vasculitis features and biallelic variants in ADA2 have been identified in ~ 25–31% of childhood PAN cases." (PMID 36807221, 2023). "Deficiency of ADA2 is also associated with vasculitis and can cause a variety of clinical presentations including early onset strokes, rashes, cytopaenias and immunodeficiency." (PMID 38068532, 2023). "Many different pathogenic mutations in the ADA2 gene were described, and the phenotype is highly variable with features of vasculitis/vasculopathy, bone marrow disease (e.g., cytopenias), and immune dysregulation (e.g., hypogammaglobulinemia) [28, 29•]." (PMID 35920952, 2022). "Adenosine deaminase 2 (ADA2) deficiency is an inherited autoinflammatory syndrome that was first described in 2014 by two independent research groups as a monogenic vasculitis resembling polyarteritis nodosa in its clinical manifestations." (PMID 36528591, 2022). "The discovery of this association between ADA2 and vasculitis has led to the reconsideration of the diagnosis in most cases of childhood-onset PAN." (PMID 33863937, 2021). "Ross, David A. Cabral and Kelly L. Brown: Identification of novel adenosine deaminase 2 gene variants and varied clinical phenotype in pediatric vasculitis." (PMID 33955503, 2021). "Deficiency of ADA2 was discovered by unbiased genetic studies in patients with early-onset vasculopathy/vasculitis who were suspected to have a monogenic disease." (PMID 29951947, 2018). "Human ADA2 deficiency (DADA2) is an inborn error of immunity (IEI) caused by biallelic deleterious mutations in adenosine deaminase 2 (autoADA2), characterized by autoinflammation in the form of recurrent fevers and vasculitis ranging from livedo racemosa to lacunar strokes." (PMID 40864493, 2025). "In addition, deficiency of adenosine deaminase 2 (DADA2) can present with vasculitis manifestations similar to PAN, which should be carefully differentiated." (PMID 39183419, 2024). "In general, patients with the vasculitis phenotype usually carry variants that determine a residual ADA2 activity up to 40%–60% of the normal range (hypomorphic mutations) unlike patients with a prominent hematological phenotype in which the residual enzymatic activity is usually <3%." (PMID 38357265, 2023). "However, missense variants with residual ADA2 activity are commonly seen in vasculitis phenotypes, whereas bone marrow failure is associated with missense, non-sense or frameshift variants and complete loss of ADA2 activity." (PMID 35774100, 2022). "For example, abatacept in CTLA4 haploinsufficiency, LRBA and DEF6 deficiencies; tocilizumab in STAT3 GOF; JAK inhibitors in STAT3 and STAT1 GOF patients; alemtuzumab for CD25 deficiency; PIK3δ inhibitors for APDS or anti-TNFα therapy for vasculitis in ADA2 deficiency." (PMID 34447369, 2021). "Whether heterozygosity for ADA2 mutation predispose to late-onset stroke, polygenic vasculitis, and other cardiovascular disease remains to be investigated." (PMID 29951947, 2018). "More strikingly however, genome-wide analysis revealed a marked overexpression of neutrophil-derived genes, suggesting that the vasculitis seen in ADA2 deficiency may be an indirect effect resulting from chronic and marked activity of neutrophils." (PMID 25278816, 2014). "Our findings suggest that the vasculitis seen in ADA2 deficiency may be an indirect effect resulting from chronic and marked activity of neutrophils." (PMID 25278816, 2014).
vasculitis (continued). "The first impression was PAN or PAN-like syndrome, which could be adenosine deaminase 2 deficiency (ADA2) or familial Mediterranean fever (FMF); therefore, she was given a referral report to perform a full vasculitis plan, as well as ADA2 and FMF gene mutations." (PMID 39239002, 2024). "Remarkably, lower patient ADA2 activity is predictive of neutropenia and shows a trend toward HCT decision, whereas higher patient ADA2 activity is predictive of vasculitis symptoms." (PMID 42312136, 2026). "Hepatic involvement with vasculitis, as well as complications such as NRH, elevated transaminases and portal hypertension are all reported in association with ADA2 deficiency." (PMID 38068532, 2023). "In patient 2, different vasculitis phenotypes of the DADA2 spectrum are presented, all resulting from the homozygous ADA2 mutation p.Y453C." (PMID 35774100, 2022). "Deficiency of adenosine deaminase-2 (DADA2), caused by mutations in ADA2, is regarded as a mimic of polyarteritis nodosa as it typically presents with a small to medium-sized vessel vasculitis leading to early-onset stroke." (PMID 36034552, 2022). "Two more recently described diseases, deficiency of adenosine deaminase 2 (DADA-2) and Haploinsufficiency A20 (HA20), can also present with vasculitis in adults [27•, 64••]." (PMID 35920952, 2022). "Additional tests frequently requested included ADA2 levels for the exclusion of DADA2, and IGRA to exclude TBC, as both conditions have been reported to cause neuroinflammation/vasculitis." (PMID 33842414, 2021). "Deficiency of adenosine deaminase 2 (DADA2) is an autosomal recessive disease associated with a highly variable clinical presentation, such as vasculitis, inflammation, and hematologic manifestations." (PMID 34721429, 2021). "ADA2 deficiency results in a predominance of M1 macrophages characterized by increased production of pro-inflammatory cytokines, such as tumor necrosis factor alpha (TNF alpha), an important mediator of vasculitis and tissue damage." (PMID 35774100, 2022). "While the absence of ADA2 enzyme activity—as seen in this patient—is typically associated with severe hematological disease, this has also been seen in vasculitis phenotypes." (PMID 35774100, 2022). "The search for ADA2 mutations and the assessment of ADA2 activity should be considered also in patients with the association of hypogammaglobulinemia and inflammatory conditions, also with late presentation and in absence of vasculitis." (PMID 37207212, 2023). "Loss-of-(catalytic)-function variants in the ADA2 gene are associated with Deficiency of ADA2 (DADA2), an autosomal recessive disease associated with an unusually broad range of inflammatory manifestations including vasculitis, hematological defects and cytopenia." (PMID 36248868, 2022). "Fingertip skin lesions including chilblain-like erythema, vasculitis, Raynaud’s phenomenon, ulceration, or necrosis may occur in systemic lupus erythematosus or in vasculitis (including in the adenosine deaminase-2 deficiency, DADA2, in which skull involvement is not commonly described)." (PMID 38791606, 2024). "Genetic testing and/or ADA2 activity detection should be considered in all patients with recurrent fever accompanied unexplained elevated CRP and/or ESR, especially in those with livedo racemosa/reticularis and evidence of PAN-like vasculitis." (PMID 36807221, 2023).